NQO1 (NAD(P)H quinone dehydrogenase 1)
Diseases named in the same sentence as NQO1 in open-access papers (continued):
Sharing a sentence is not in itself a finding about the gene and the disease.
gastritis (1 paper, 2025). Inflammation of the stomach. "In summary, the prevention and therapy of VE have significant protective effects on stress‐induced gastritis via promoting Nrf2/Hmox1/NQO1 and inhibiting NF‐κB signalling pathways." (PMID 40418631, 2025). "VE displayed significant antioxidant properties in stress‐induced gastritis via activating the Nrf2/Hmox1/NQO1 pathway." (PMID 40418631, 2025). "Consequently, it can be considered that the Nrf2/Hmox1/NQO1 pathway is most likely responsible for mediating the oxidative stress‐resistant properties of VE in stress‐induced gastritis." (PMID 40418631, 2025).
glomerular disease (1 paper, 2023). "We evaluated the podocyte expression of NFE2L1, Nuclear Factor Erythroid 2-related Factor 2 (NFE2L2), and NAD(P)H:quinone Oxidoreductase (NQO1) in 127 human glomerular disease biopsies using multiplexed immunofluorescence and image analysis." (PMID 37681897, 2023).
Heat Stroke (1 paper, 2026). A condition caused by the failure of body to dissipate heat in an excessively hot environment or during PHYSICAL EXERTION in a hot environment. "Transcriptomic analysis showed that NRF2 and its downstream gene NAD(P)H quinone oxidoreductase 1 (NQO1) were expressed at significantly lower levels in patients with severe heat stroke compared than in healthy controls and mild cases." (PMID 42079625, 2026). "Early after severe heat stroke, NRF2 and its downstream antioxidants HO-1 and NQO1 were significantly downregulated, suggesting that impaired NRF2-mediated antioxidant defense promotes disease pathogenesis." (PMID 42079625, 2026).
hypertriglyceridemia (1 paper, 2015). A laboratory test result indicating elevated triglyceride concentration in the blood. "Our data suggest that polymorphisms of HMOX1 and NQO1 genes are associated with a high risk of metabolic disorders, including high systolic and diastolic blood pressure, hypertriglyceridemia, and low HDL-c levels in Mexican Mestizo individuals." (PMID 25933176, 2015). "The present study provides additional evidence that polymorphisms of the HMOX1 and NQO1 genes are associated with high risk in metabolic disorders, such as blood systolic and diastolic pressure, hypertriglyceridemia, and low levels of HDL-c." (PMID 25933176, 2015). "Likewise, the NQO1 609T allele displayed an association with hypertriglyceridemia and low levels of HDL-c, but only within the group of individuals suffering MetS." (PMID 25933176, 2015). "After adjustment for age, gender, and BMI, we also observed a significant association of NQO1 C609T SNP with low HDL-c level (OR = 7.7, P = 0.04) and hypertriglyceridemia (OR = 2.6, P = 0.04) but only among individuals suffering MetS." (PMID 25933176, 2015).
insomnia (1 paper, 2025). A sleep disorder characterized by difficulty in falling asleep and/or remaining asleep. "In this study, we showed that Keap1 expression was increased and Nrf2, NQO1, and HO‐1 expression was decreased in insomnia rats, and after senegenin intervention, Keap1 expression was decreased and Nrf2, NQO1, and HO‐1 expression was increased." (PMID 39380353, 2025).
intrahepatic cholangiocarcinoma (1 paper, 2014). A carcinoma that arises from the intrahepatic bile duct epithelium in any site of the intrahepatic biliary tree. "However, the alternative hypothesis seems to be true with low NQO1 expression evaluated by IHC in intrahepatic cholangiocarcinoma (ICC) cases predicting poor prognosis." (PMID 24499631, 2014).
kidney injuries (1 paper, 2020). "NAD(P)H:quinone oxidoreductase 1 (NQO1) is an antioxidant enzyme that has been involved in the progression of several kidney injuries." (PMID 33082368, 2020).
laryngeal squamous cell carcinoma (1 paper, 2023). A squamous cell carcinoma that arises from the larynx. "For example, radiation-resistant tumors of early-stage laryngeal squamous cell carcinoma patients had increased the tumor mutation burden and NQO1 expression." (PMID 37583897, 2023).
Leber hereditary optic neuropathy (1 paper, 2018). Leber's hereditary optic neuropathy (LHON) is a mitochondrial neurodegenerative disease affecting the optic nerve and often characterized by sudden vision loss in young adult carriers. "On the other hand, idebenone, a compound recently approved for treatment of Leber's hereditary optic neuropathy (LHON) disease, increases intracellular ATP production and decreases lactate levels in MELAS cybrid cells in a NQO1-dependent manner." (PMID 30026729, 2018).
leiomyosarcoma (1 paper, 2022). An uncommon, aggressive malignant smooth muscle neoplasm, usually occurring in post-menopausal women. "Compared to other histological types, leiomyosarcoma showed high expression of HELLS, EPAS1, NQO1 and low expression of IL6." (PMID 34982796, 2022).
lentivirus infection (1 paper, 2019). Virus diseases caused by the Lentivirus genus. "Conversely, when we overexpressed NQO1 in TE-11R cells via lentivirus infection, NQO1 overexpression resulted in a decrease of 8-OHdG-indicated oxidative damage after THC treatment and was associated with resistance to THC treatment." (PMID 30737573, 2019).
lipodystrophy (1 paper, 2023). A congenital or acquired disorder characterized by abnormal loss or redistribution of the adipose tissue in the body. "Nqo1-null mice exhibit significantly lower levels of abdominal adipose tissue mass along with higher hepatic levels of triglycerides in the adult, which is a similar phenotype of lipodystrophy." (PMID 37686150, 2023).
liposarcoma (1 paper, 2015). A usually painless malignant tumor that arises from adipose tissue. "Statistically significant under-expression of NQO1 was discovered in liposarcoma and soft tissue sarcoma." (PMID 27625902, 2015).
liver inflammation (1 paper, 2020). "Our study demonstrated that APAP and ROX co-treatment significantly increased the expression levels of TNF-α, INF-γ, VCAM-1, CXCL-1, STAT-3, Nrf-2, GSTA, GCLC-1, HO-1 and NQO1, suggesting that APAP and ROX co-treatment can induce liver inflammation." (PMID 32132876, 2020).
lung carcinoids (1 paper, 2019). "Despite all these considerations, the KEAP1 silencing studies support the hypothesis that KEAP1 acts in lung carcinoids by modulating the levels of NRF2 and the NRF2-detoxification enzymes TXNRD1 and NQO1." (PMID 31126053, 2019).
lupus nephritis (1 paper, 2022). Glomerulonephritis in the context of systemic lupus erythematosus. "A larger study on Lupus-nephritis (LN) kidney biopsies reported a significant increase in Nrf2 and NQO1 protein in the LN glomeruli compared to normal kidney tissue." (PMID 35740009, 2022). "Likewise, in kidney tissue from patients with Lupus nephritis, who presented with pronounced proteinuria but apparently normal GFR, the glomerular protein amount of Nrf2 and NQO1 was increased compared to healthy kidney tissue, and signs of oxidative damage of the glomeruli were present." (PMID 35740009, 2022).
metastatic cancer (1 paper, 2025). A carcinoma which has spread from the original site of growth to another anatomic site. "According to another study, metastatic cancer patients who received chemotherapy had SOS genes including NQO1 and PON1 as notable predictors of their prognosis." (PMID 39958338, 2025).
migraine (1 paper, 2025). "NQO1 plays a vital role in various aspects of cellular functioning, including antioxidant defense, and may thus link migraine with oxidative stress through SIRT2." (PMID 40724883, 2025). "The upregulation of SIRT2 restores the expression of the NFE2L2 gene, which encodes NRF2 and NQO1, while also decreasing oxidative stress in the injured spinal cord of rats, which leads to improvements in thermal hyperalgesia and mechanical allodynia, highlighting the potential of SIRT2 in migraine." (PMID 40724883, 2025).
Mm (1 paper, 2024). "Additionally, our results demonstrated that SA exerts an antioxidative effect on Mm infection by activating the AMPK-α1/AKT/GSK-3β signaling pathway and upregulating the expression of NRF2/HO-1/NQO-1." (PMID 38399751, 2024).
multinodular goiter (1 paper, 2025). Nodular goiter characterized by more than one discrete tissue mass. "In the patient with multinodular goiter who did not harbor a KEAP1 mutation, TG expression in the nodule was equivalent to that in the nonnodular parenchyma, while NQO1 and GPX2 expression was very low in both regions." (PMID 39373520, 2025).
Nasal polyposis (1 paper, 2022). Polypoidal masses arising mainly from the mucous membranes of the nose and paranasal sinuses. "Therefore, it is suspected that NQO1 upregulation possibly reflects polyp tissue proliferation during nasal polyposis." (PMID 36290622, 2022).
neural tumor (1 paper, 2013). "To further elucidate the mechanism by which NQO1 influences mitochondrial function in human neural tumor cells, we measured activities of mitochondrial complexes I and II in cells expressing high or lower levels of NQO1." (PMID 23874855, 2013).
oral mucositis (1 paper, 2020). Inflammation of the mucous membranes of any of the structures in the mouth. "Animals with oral mucositis treated with AuNp (250 μg/kg) had increased mRNA levels of the antioxidant enzyme NQO1 (NAD (P) H quinone dehydrogenase 1), compared to the 5-FU animals (p < 0.0001 vs. 5-FU)." (PMID 32230975, 2020).
paraganglioma (1 paper, 2023). A benign or malignant neoplasm arising from paraganglia located along the sympathetic or parasympathetic nerves. "Compared to normal tissue, NQO1 mRNA is highly expressed in most tumors, except for kidney chromophobe, pan-kidney cohort, kidney renal papillary cell carcinoma, pheochromocytoma and paraganglioma, and wilms tumor." (PMID 37583897, 2023).
primary biliary cirrhosis (1 paper, 2020). "NQO1 is protective against acetaminophen (APAP)-induced hepatotoxicity and is increased in APAP-associated DILI and primary biliary cirrhosis." (PMID 32660103, 2020).
prostatic intraepithelial neoplasia (1 paper, 2020). "NQO1 was detectable mainly in the cytoplasmic compartment of epithelial cells from benign, high-grade prostatic intraepithelial neoplasia (PIN), and infiltrating adenocarcinoma." (PMID 31909204, 2020).
Renal cyst (1 paper, 2011). A fluid filled sac in the kidney. "Similarly, Nrf2 and Nqo1 are both increased in cells lining Fh1-associated renal cysts." (PMID 22014577, 2011). "Renal cysts from both groups manifest increased nuclear expression of Nrf2; elevated expression in cysts was particularly striking for Nqo1 as compared with the interstitium and some noncystic tubules." (PMID 22014577, 2011).
selenium deficiency (1 paper, 2024). A nutritional deficiency disease resulting from inadequate selenium levels in the body, which can lead to impaired function of selenoproteins essential for antioxidant defense and thyroid hormone metabolism. "The activation of NRF2 upon selenium deficiency is discussed to compensate for the loss of antioxidant selenoproteins by upregulating selenium-independent antioxidant proteins such as NQO1, HMOX1, and glutathione transferases." (PMID 39456464, 2024). "However, even though GPX4 and TXNRD1 expression were both decreased after 72 h of selenium deficiency, there was no increase in NQO1 activity or protein under these conditions." (PMID 39456464, 2024).
skin inflammation (1 paper, 2023). "The protective effects of PF and PW on UVB-induced skin inflammation and skin barrier damage in human immortalised epidermal keratinocytes (HaCaT) cells (including cell viability, ROS, HO-1, NQO1, IL-1β, IL-8, TNF-α, KLK-7, FLG, AQP3 and Caspase 14 levels) are investigated." (PMID 36771204, 2023).
Spinocerebellar ataxia (1 paper, 2024). "For NQO1, “Proteasome”, “Protein processing in endoplasmic reticulum”, “Spinocerebellar ataxia”, “Bacterial invasion of epithelial cells”, and “Nucleocytoplasmic transport” were activated most significantly." (PMID 39328407, 2024).
systemic lupus erythematosus (1 paper, 2025). An autoimmune multi-organ disease typically associated with vasculopathy and autoantibody production. "In Gloms, Ribosome (NES = −2.36), Complement/coagulation (−2.28), Gap junction (−2.22), and Systemic lupus erythematosus (−2.11) were markedly suppressed, indicating diminished protein synthesis, immune regulation, and cell–cell communication under NQO1 deficiency." (PMID 40920692, 2025).
T-cell lymphoma (1 paper, 2023). "Genomic response by antioxidant signaling inducers suggest NAD(P)H:quinone oxidoreductase 1 (NQO1) and glutathione S-transferase (GST) are the two main target genes activated through Nrf2 in T-cell lymphoma." (PMID 37274286, 2023).
thyroid nodule (1 paper, 2025). A small circumscribed mass in the THYROID GLAND that can be of neoplastic growth or non-neoplastic abnormality. "Immunohistochemical analysis of TG, NQO1, and GPX2 was performed using thyroid tissues of the same patient with the L136P mutation, and FC values in the thyroid nodule were 1.04, 55.47, and 496.64, respectively." (PMID 39373520, 2025).
thyroid tumor (1 paper, 2025). A benign or malignant neoplasm affecting the thyroid gland. "While Ogg1 mRNA expression was not modified, we observed a downregulation of Gpx2 and Nqo1 mRNA expression in thyroid tumors from 2- and 8-month-old RET/PTC3 Dicer1(+/+) mice compared to WT thyroids, suggesting that redox homeostasis is unbalanced in RET/PTC3 tumors." (PMID 41002430, 2025).
uremia (1 paper, 2017). A clinical syndrome associated with the retention of renal waste products or uremic toxins in the blood. "In advanced uremia, in dialysis patients (n = 34), NQO1 gene expression was less robustly upregulated than that in CKD 1–5, while NQO1 protein was not upregulated." (PMID 28785379, 2017). "Moreover, we found that in more pronounced uremia (CKD 5D), the NQO1 gene expression was less upregulated than that in CKD 1–5 and NQO1 protein content was not increased." (PMID 28785379, 2017).
cancer (409 papers, 1995 to 2026). A tumor composed of atypical neoplastic, often pleomorphic cells that invade other tissues. "Some research studies have focused on identifying both inhibitors and activators of NQO1 from natural sources, with inhibitors showing particular promise in increasing cancer cell susceptibility to treatment." (PMID 40002465, 2025). "Previous studies conducted in Turkish populations have investigated the role of the NQO1 C609T polymorphism in various cancers." (PMID 41010895, 2025). "The biological potential of hybrids was examined by designation of the enzymatic conversion rate of the NQO1 protein and in vitro against cancer cell lines with overexpression of the gene encoding the NQO1 protein." (PMID 40508142, 2025). "For instance, a meta-analysis that included 28 relevant studies involving 5,953 patients with acute leukemia and 8,667 controls has shown an increased risk of cancer for carriers of the NQO1 C609T polymorphism." (PMID 38167027, 2024). "The 3423G is another NQO1 polymorphism, which has been accompanied by decreased enzyme activity and enhanced risk of cancer." (PMID 38167027, 2024). "A meta-analysis involving 92 studies, which included 21,178 patients with various types of cancer and 25,157 healthy controls, indicates the implication of C609T polymorphism of the NQO1 gene as a genetic risk factor in different cancers." (PMID 38167027, 2024). "Consistent with an antioxidant role, a susceptibility to cancer development and cardiovascular and other diseases has been linked to decreased NQO1 activity." (PMID 39120303, 2024). "Multiple polymorphisms in the NQO1 gene have been associated with altered enzyme activity, which has implications for various health conditions, including cancer, cardiovascular diseases, and neurological disorders." (PMID 38167027, 2024). "To validate the potential regulatory function of NQO1 in cell cycle progression at the G2/M phase in cancer cells, we determined the protein levels of associated cyclin B1 and CDK1." (PMID 36793872, 2023). "Subsequently, we evaluated the correlations between the NQO1 expression and the tumor mutation burden, microsatellite instability, immune infiltration levels, and various immune-related genes in multiple cancer types." (PMID 37583897, 2023). "The data showing that disruption of the NQO1 gene or genetic variation enhanced the risk of chemical-induced toxicity and cancer paradoxically showed the antioxidant role of NQO1 despite the biological functions of this "cell protector"106,107." (PMID 37699912, 2023). "NHEJ was slightly decreased in irradiated cancer cells deficient for NQO1/c-Fos/CKS1 signaling but was slightly increased in cells where this signaling pathway remained active." (PMID 36793872, 2023). "NQO1 encodes a reductase that regulates oxidative stress of chromatin binding-proteins for DNA damage in cancer cells." (PMID 36894886, 2023). "As is essential for this manuscript, it must be noted that alterations in NQO1 activity are also associated with certain diseases linked, to different extents, with oxidative stress, such as cancer, Alzheimer’s disease, Parkinson’s disease and atherosclerosis." (PMID 36829939, 2023). "Loss of NQO1 and its activity will limit a cancer cell’s ability to survive in detached conditions, thus impacting a tumor cell’s metastatic potential." (PMID 36980879, 2023). "Overexpression of c-Fos in NQO1-deficient cancer cells enhanced radioresistance, an effect that was blunted by siRNA-mediated knockdown of CKS1B." (PMID 36793872, 2023). "Given the significant involvement of CKS1 in cancer cell growth, invasion, metastasis and drug resistance 45, our findings offer a possible mechanistic explanation for the association of NQO1 overexpression with poor clinical outcomes in cancer patients." (PMID 36793872, 2023). "Remarkably, certain genetic variations in NQO1 have been associated with cancer development, possibly due to a loss of activity and stability." (PMID 36829939, 2023).